MTOR (mechanistic target of rapamycin kinase)
Diseases named in the same sentence as MTOR in open-access papers (continued):
Sharing a sentence is not in itself a finding about the gene and the disease.
Alzheimer disease (continued). "The dysfunction of the signaling pathways downstream of mTOR may represent a risk factor for Alzheimer’s disease and is independent of the ApoE status of the patients." (PMID 24252508, 2013). "Trained immunity in microglia, driven by epigenetic reprogramming (e.g., increased H3K4me1 and H3K27ac), exacerbates cerebral β-amyloidosis in Alzheimer’s disease, particularly through HIF-1α and mammalian target of rapamycin (mTOR) pathways." (PMID 39655962, 2025). "Together, these findings indicate that the mTOR/4E-BP1 axis plays a central role in tau protein homeostasis and Alzheimer’s disease pathogenesis." (PMID 41286527, 2025). "Prompt cognitive recovery and severe mTOR inhibition has also been demonstrated in other early onset (EOAD) and late-onset Alzheimer’s disease (LOAD) mouse models upon prompt treatment for 13 to 16 weeks after clinical onset." (PMID 38139306, 2023). "Wnt/mTOR pathway and behavioral alterations in rodent models of attention-deficit hyperactivity disorder (ADHD) and Alzheimer’s disease (AD)." (PMID 36875654, 2023). "Overexpression of circNF1-419 regulated cellular autophagy through the PI3K-1/Akt-AMPK-mTOR and PI3K-1/Akt-mTOR signaling pathways in astrocytes, providing a new strategy for the treatment of Alzheimer’s disease." (PMID 35313983, 2022). "Different genes express identified Pathways such as Notch signaling pathways relating to Alzheimer’s disease, peroxisome proliferator-activated receptor (PPAR), adipocytokine, insulin, PI3K–Akt, mTOR, and AMPK signaling pathways." (PMID 34306005, 2021). "Resveratrol also promotes clearance of Aβ peptides, likely via inhibition of mTOR and activation of AMPK and prevents cognitive impairment in different cell lines and models of Alzheimer’s disease." (PMID 34206738, 2021). "The mammalian target of rapamycin (mTOR) complex 1 (mTORC1) suppresses the initiation of autophagy by phosphorylating ULK1, and mTOR activity is upregulated in Alzheimer disease, Parkinson disease, and Huntington disease." (PMID 31552299, 2019). "Rapamycin, an inhibitor of mammalian target of rapamycin (mTOR), can restore CBF and brain vascular density (BVD) via regulating nitric oxide (NO) release in Alzheimer's disease (AD) mice." (PMID 31410191, 2019). "The hyperphosphorylation of tau protein and the overexpression of mTOR are considered to be the driving force behind Aβ plaques and Neurofibrillay Tangles (NFT's), hallmarks of Alzheimer's disease (AD)." (PMID 30686983, 2018). "In cell models of Alzheimer’s disease, Aβ degeneration of microglia is limited by EPO through combined activation of PI 3-K and mTOR pathways." (PMID 23109841, 2012). "Additionally, dichotomine B is a key bioactive compound that mitigates Alzheimer’s disease pathology by inducing autophagy and activating the PI3K/Akt/mTOR and AMPK signaling pathways." (PMID 41011730, 2025). "In Alzheimer's disease mice, exogenous IFN‐γ improved the neurological symptoms by attenuating the stimulation of β amyloid to microglia through promoting glycolysis by activating mTOR pathway." (PMID 37132040, 2023). "In a mouse model for Alzheimer’s disease, exogenous interferon-γ (IFN-γ) attenuated neurological deficits by attenuating the stimulation of β amyloid to microglia through promoting glycolysis by activating mTOR pathway." (PMID 35669777, 2022). "We find that knockdown of Tsc1 and mTor gene expression, does not significantly increase or decrease tau aggregate counts in rat neurons incubated with tau seeds extracted from human Alzheimer’s disease brains." (PMID 34127790, 2021). "The mTOR inhibition has been reported to reduce or prevent BBB breakdown in several models of neurological disorders, including cerebral ischemia-reperfusion injury, Alzheimer’s disease, subarachnoid hemorrhage, and status epilepticus." (PMID 34226528, 2021).
Alzheimer disease (continued). "However, the literature suggests that mTOR is already upregulated in Alzheimer disease brains, animal models, and in Down Syndrome whose patients exhibit accelerated AD pathogenesis." (PMID 31396078, 2019). "Aberrant activation of neuronal PI3K/AKT/mTOR and PTEN signaling may be an early prelude of Alzheimer disease." (PMID 26168237, 2015). "However, this mTOR dependent IGF-1/IGFBP5 signaling pathway has not yet been studied in the hippocampus in the context of Alzheimer’s disease and needs further investigation." (PMID 35513854, 2022). "Conversely, antidepressant drugs activating the PI3K/Akt/mTOR pathway, a common mechanism in rapid-acting antidepressants, may accelerate aging in MDD patients, making them unsuitable for those with comorbid aging-related conditions like dementia and Alzheimer’s disease." (PMID 38926475, 2024). "In Alzheimer's disease, TSC1 aggregates form in the absence of TSC2 in the CA1 region of the hippocampus, leading to increased inflammation, altered autophagy, β‐amyloid accumulation and cell death via mTOR." (PMID 39962362, 2025).
type 2 diabetes (219 papers, 2009 to 2026). "We show that the G-allele of the lead variant, rs4845987, which is associated with decreased risk of type 2 diabetes, reduces MTOR expression in T cells and improves survival in sepsis due to pneumonia, with effects specific to sepsis endotype." (PMID 41741465, 2026). "While mTOR is crucial for muscle hypertrophy, its chronic hyperactivation has been implicated in diseases such as type 2 diabetes, cancer, and neurodegenerative conditions." (PMID 41356921, 2025). "The regulatory effect of matrine on mTOR provides a new idea for the treatment of type 2 diabetes-associated AS." (PMID 36744254, 2023). "Several pathways were selected as the key action mechanism underlying DKD treatment with Forsythiaside, including Type II diabetes mellitus and mTOR signaling pathways." (PMID 36712665, 2022). "Uncoupling of downstream insulin signalling at the PI3k-Akt-mTOR axis in various cell types including hepatocytes and adipocytes has been directly implicated in the development of insulin resistance and type 2 diabetes." (PMID 35327652, 2022). "mTOR signaling dysfunction has been associated with type 2 diabetes, cancer, neurodegeneration and ageing." (PMID 36042901, 2022). "Dysregulation of mTOR is associated with numerous human diseases, such as type 2 diabetes, cancer, and neurodegeneration, and the development of mTOR inhibitors is actively being pursued, particularly in oncology." (PMID 31409554, 2021). "What actually contributes to type 2 diabetes is excess of nutrients (and especially carbohydrates), which activate mTOR and cause hyperinsulinemia and insulin resistance." (PMID 32534452, 2020). "mTOR signaling is the central pathway in response to the environment, and the disruption of mTOR signaling is associated with developmental defects, cancer, neurodegenerative diseases, type 2 diabetes, autoimmune diseases, and aging-related diseases." (PMID 31547370, 2019). "It has also been pointed out that the “starvation induced diabetes” associated with mTORC1 inhibition differs substantially from type II diabetes, which is caused by insulin resistance resulting from overnutrition and is associated with mTOR activation." (PMID 24379984, 2013). "The network pharmacology results also showed that SN0224203 might act as an α-amylase inhibitor, it was found to be associated with various genes like GCK, VDCC, PIK3, and mTOR and Type II diabetes mellitus pathway." (PMID 41674321, 2026). "mTOR signaling dysregulation is linked to a variety of diseases, including type 2 diabetes." (PMID 37569434, 2023). "Based on the results of previous studies, we speculated that LINC01480 inhibits the development of ICM by downregulating the mTOR signaling pathway to reduce the risk of type II diabetes mellitus." (PMID 35557532, 2022). "Moreover, the pathways enriched fast evolving genes include insulin signaling pathway, mTOR signaling pathway, and type II diabetes-associated pathways, all of which are important for the regulation of blood glucose." (PMID 28900766, 2018). "Type II diabetes and starvation diabetes seem to be the two opposite conditions: the first is associated with activation of nutrient-sensing pathways, whereas the second is associated with deactivation of nutrient sensing pathways such as mTOR." (PMID 22683661, 2012). "The mTOR pathway is activated during various cellular processes and its function has been implicated in multiple diseases, including tumor formation, angiogenesis, insulin resistance, adipogenesis, and is deregulated in pathological conditions (e.g., cancer and type 2 diabetes)." (PMID 36470863, 2022). "As a well-established AMPK activator and mTOR inhibitor, metformin is widely prescribed for type 2 diabetes, with over 200 million users worldwide." (PMID 41303544, 2025). "Type 2 diabetes and the mammalian target of rapamycin (mTOR) signaling pathway ranked highest, with IRS1 among the overlapping genes." (PMID 40243885, 2025).
type 2 diabetes (continued). "Previous studies have found that the mTOR signaling pathway and the lysosomal pathway are closely related to type 2 diabetes." (PMID 40951426, 2025). "While the biguanide drug metformin, commonly used to treat type 2 diabetes, decreased the staining drastically, comparable to navitoclax, the mTOR inhibitor rapamycin only slightly affected the β-gal staining." (PMID 37644339, 2024). "In this study, we assessed urinary excretion of molecular regulators of these processes that mediate their effects via the PI3K/AKT/mTOR pathway in subjects with long-term type 2 diabetes (T2D) and different patterns of chronic kidney disease (CKD)." (PMID 38540101, 2024). "Metformin, a medication frequently prescribed to treat type 2 diabetes, has been demonstrated to suppress excessive protein synthesis by inhibiting the mTOR (mammalian target of rapamycin) and ERK pathways." (PMID 39022311, 2024). "An over-activation of the mechanistic target of rapamycin (mTOR) pathway promotes senescence and age-related diseases like type 2 diabetes." (PMID 38748336, 2024). "On the other hand, the upregulated miRNAs demonstrate predictive function in regulating FoxO, Ras, TGF‐β, Pi3K‐Akt, MAPK, mTOR, insulin signaling, and type II diabetes mellitus." (PMID 38751007, 2024). "Most studies have demonstrated lower autophagy activity in cardiomyocytes of type 1 and type 2 diabetes due to activated mammalian target of rapamycin(mTOR) and inhibited AMPK and transcription factor EB(TFEB) signalling in diabetic hearts." (PMID 36562207, 2023). "mTOR signaling is also frequently activated in cancer and is associated with various diseases, including obesity, metabolic syndrome, and type 2 diabetes mellitus (t2DM)." (PMID 37573301, 2023). "Metformin is an oral biguanide frequently used to treat type 2 diabetes, well known by mTOR inhibition." (PMID 36769263, 2023). "In conclusion, we have used cell studies to provide evidence that the well-tolerated type 2 diabetes drug metformin inhibits mTOR signaling by a different mechanism than rapamycin, through suppressing BCAA and glutamine uptake." (PMID 37302544, 2023). "Advanced glycosylation end products (AGEs) are a group of substances existing in poorly controlled type 2 diabetes mellitus, which promote the fibrotic response of VSMCs and then aggravate AS through mTOR signaling pathway activation." (PMID 36744254, 2023). "Metformin, an FDA-approved mammalian target of rapamycin (mTOR) inhibitor, is the first-line hypoglycemic drug for treating type 2 diabetes and metabolic syndrome." (PMID 35769369, 2022). "And the overlapping pathways, including mTOR signaling pathway and Type II diabetes mellitus were identified as the key pathways that Forsythiaside ameliorated DKD by improving podocytopathy." (PMID 36712665, 2022). "S6K1 is a recognized signal molecule in the insulin signaling pathway PI3K/AKT/mTOR which plays an important role in the pathogenesis of type 2 diabetes." (PMID 36062190, 2022). "Bathina and Das examined the alteration of the PI3K/Akt/mTOR pathway in the brain of streptozotocin-induced type 2 diabetes rats." (PMID 35528246, 2022). "Downregulation of the mTOR/4E-BP1 signaling pathway in type 1 diabetes.Inhibition of glucagon signaling in type 2 diabetes." (PMID 36555754, 2022). "The pathways of Forsythiaside in the treatment of DKD were mTOR signal pathway and Type II diabetes mellitus." (PMID 36712665, 2022). "Upregulated gene expression pathways in high VAT patients included several carbohydrate metabolism pathways including maturity-onset diabetes of the young, glycosaminoglycan degradation, galactose metabolism, as well as mTOR signaling." (PMID 35087143, 2022). "The top KEGG pathways were the mTOR signaling pathway, Type II diabetes mellitus, and Rap1 and Ras signaling pathway." (PMID 36712665, 2022).
type 2 diabetes (continued). "Abnormalities of “mTOR signaling pathway” and “MAPK signaling pathway” are associated with a variety of diseases, such as type 2 diabetes, cancer, neurodegenerative diseases, cardiovascular diseases, and autoimmune diseases." (PMID 35619068, 2022). "The mTOR signaling pathway seems to be involved in both type 1 and type 2 diabetes, insulin production being reduced in type 1 diabetes due to the destruction of pancreatic β cells while insulin resistance occurs in type 2." (PMID 34069618, 2021). "Metf is a widely used drug for the treatment of type 2 diabetes that inactivates mTOR, with demonstrated antitumoral properties." (PMID 32183017, 2020). "As such, mTOR complexes and their downstream targets are actionable proteins and metabolic targets in managing type 2 diabetes and mediate mTOR central role in glucose and energy metabolism and in pancreatic progenitor cell growth." (PMID 32978410, 2020). "On the other hand, the present results indicate that autophagy is activated in the hippocampus 24 h after GI in an AMPK-dependent mTOR-independent manner in rats exposed to coma." (PMID 33173467, 2020). "The work provides insights and tools for studies seeking to develop drugs that target the mTOR substrate phosphorylation pathway for the treatment of cancer, type II diabetes and age related disease." (PMID 30833605, 2019). "Modification of Cpt1a and mTOR gene expression by coffee in a type-2 diabetic model that is being reported for the first time here can be an important mechanism by which coffee improves carbohydrate metabolism and reduces the risk of T2D." (PMID 31484373, 2019). "SREBP-1 positively correlates with mTOR activity, and both are upregulated in animal models of type 2 diabetes and in cancer." (PMID 29723221, 2018). "Due to the strong links between mTOR signalling and insulin signalling, many efforts have been made to create mathematical models of the two combined especially in the area of Type 2 diabetes mellitus (T2DM)." (PMID 28096317, 2017). "The top 20 most significant enriched pathways included pathways in cancer, insulin signalling pathway, type 2 diabetes and mTOR signalling." (PMID 28643459, 2017). "In the context of this manuscript, other significantly enriched pathways such as mTOR signaling (rank 9, −log(P value) = 1.85) and type II diabetes mellitus signaling (rank 16, −log(P value) = 1.51) are also highly relevant." (PMID 28396702, 2017). "Calorie restriction (CR), which deactivates the nutrient-sensing mTOR pathway, slows down aging and prevents age-related diseases such as type II diabetes." (PMID 22683661, 2012). "In conclusion, our data indicate impaired AKT/mTOR signaling exists in fibroblast cells derived from steatosis patients and that numerous features typical for diabetes type 2 were also observed in steatosis patients." (PMID 22969728, 2012). "Our work suggests that the widely used anti-type II diabetes drug metformin can suppress mTOR signaling through activation of AMPK in the hippocampus." (PMID 20126541, 2010). "Our data extend these observations and suggest that mTOR regulates the ER stress response to nutrient overload in pathological metabolic states such as type 2 diabetes." (PMID 19305497, 2009). "mTOR is a highly conserved serine/threonine kinase that is part of two distinct multi-protein complexes, mTOR complex 1 (mTORC1) and 2 (mTORC2), which are well studied in diseases such as cancer and type 2 diabetes." (PMID 40362470, 2025). "Therapeutic approaches for type 2 diabetes often target the mTOR pathway." (PMID 41356921, 2025). "Similarly, in kidney disorders such as diabetic nephropathy, exosomes from adipose-derived stem cells have been shown to enhance autophagy flux, alleviate podocyte injury and improve symptoms in type 2 diabetic mice by inhibiting mTOR signaling activation." (PMID 41390431, 2025).